MGMT (O-6-methylguanine-DNA methyltransferase)
Diseases named in the same sentence as MGMT in open-access papers (continued):
Sharing a sentence is not in itself a finding about the gene and the disease.
glioma (continued). "The detection of several molecular markers, including IDH1 mutation, 1p/19q codeletion, MGMT promoter methylation status has been applied with clinical diagnoses of gliomas, we analyzed whether LMO1 expression was correlated with some molecular genetic characteristics by using CGGA database." (PMID 35280742, 2022). "Consequently, most gliomas positive for IDH mutations also exhibit MGMT promoter methylation." (PMID 33801310, 2021). "In the CGGA glioma dataset, the risk score of the signature of the 19 ferroptosis-related genes was negatively correlated to the expression level of the well-recognized gene MGMT for TMZ resistance, verifying the results for the risk scores of resistant cells cultured in vitro." (PMID 32733879, 2020). "The MGMT promoter methylation status was found to be an important indicator of chemosensitivity in gliomas, and the correlations between the risk score and MGMT promoter methylation status suggests that the former might be related to chemotherapeutic drug sensitivity." (PMID 33230136, 2020). "Glioma cells can develop resistance against Tmz by inducing the repair of DNA damage via expression of proteins such as O6-alkylguanine DNA alkyltransferase (AGT) that demethylates Tmz-methylated guanosine encoded in humans by the O-6-methylguanine-DNA methyltransferase (MGMT) gene." (PMID 31231472, 2019). "Thus, the T/T genotype of MGMT rs12917 may have been associated with an increased risk of cancer in cases, especially the glioma cases, in the Caucasian population." (PMID 30232235, 2018). "In addition, we also investigated whether HOXA-AS3 affects IDH1 mutation and MGMT promoter methylation in glioma cells." (PMID 28881797, 2017). "In conclusion, QX302 demonstrates potent anti-glioma activity by inducing DNA alkylation and cross-linking, even in MGMT-positive cells, leading to DNA damage, cell cycle arrest, ferroptosis and apoptosis." (PMID 41513607, 2026). "Glioma prognosis is shaped by molecular markers such as IDH mutation, WHO grade, and MGMT methylation, yet heterogeneity persists within defined subgroups." (PMID 42196180, 2026). "Prior research has demonstrated that CBD can downregulate MGMT expression in glioma cells, particularly in vitro, through mechanisms involving oxidative stress and modulation of epigenetic pathways." (PMID 41596406, 2026). "This RNA regulatory editing approach offers a proof-of-principle for CRISPR mediated therapeutics in patients with MGMT unmethylated gliomas." (PMID 41817895, 2026). "Currently, common molecular markers associated with the prognosis of glioma include IDH, MGMT, telomerase reverse transcriptase (TERT), the short arm of chromosome 1 and the long arm of chromosome 19 (1p/19q)." (PMID 40860684, 2025). "In conclusion, this study identified multifocal lesions, larger tumor size, and higher WHO grade as independent adverse prognostic factors in glioma, while chemotherapy, IDH1/2 mutations, and MGMT promoter methylation were associated with improved survival." (PMID 41398783, 2025). "Specifically, our model simultaneously predicts critical glioma biomarkers including IDH mutation, 1p/19q co-deletion, MGMT promoter methylation, and WHO tumor grade (II, III, IV), while precisely delineating the tumor's T2-weighted hyperintense region." (PMID 41293309, 2025). "ADC values, particularly rADCmin, were identified as non-invasive biomarkers for MGMT methylation prediction in IDH-wild-type gliomas." (PMID 40958862, 2025). "MGMT promoter methylation is a critical predictive biomarker in high-grade gliomas (HGG), but its assessment currently relies on invasive tissue sampling." (PMID 41584616, 2025). "There were 47 patients with MGMT-methylated rHGGs: 12 with primary grade 3 gliomas and 8 with primary grade 4 gliomas who received the BAC regimen and 27 who received BEV alone." (PMID 40746950, 2025).
glioma (continued). "In this study, we aim to investigate the value of radiomic features derived from structural MRI, DCE, and DTI in predicting MGMT methylation status in glioma patients." (PMID 39944537, 2025). "The role of autophagy, IDH and MGMT mutations, and poly-ADP-ribose polymerases has also been implicated in the pathogenesis of gliomas." (PMID 40428422, 2025). "Currently, guidelines from the National Comprehensive Cancer Network (NCCN) recommend MGMT testing for all patients with high grade glioma." (PMID 39907975, 2025). "Reactive astrocytes, stimulated by gliomas, have also been known to increase the expression of MGMT (a DNA repair protein) to resist TMZ treatment." (PMID 41221443, 2025). "A notable molecule in glioma is MGMT, whose promoter methylation status serves as an independent prognostic indicator." (PMID 40110038, 2025). "In IDH-mutant gliomas, methylation within the promoter region of MGMT serves as a prognostic biomarker for extended disease-free survival and life expectancy, offering valuable prognostic information." (PMID 41551155, 2025). "Loss of MMR function is now recognized as a key mechanism of acquired TMZ resistance in gliomas, particularly in tumors with MGMT promoter methylation." (PMID 41169667, 2025). "We therefore knocked out MGMT using CRISPR/Cas9 in U1242 glioma cells as a potential tool to investigate possible alternate MGMT biological effects." (PMID 40336841, 2025). "O6-methylguanine-DNA methyltransferase (MGMT) is also an important prognostic marker for glioma patients." (PMID 40757022, 2025). "In lower grade gliomas, MGMT promoter silencing is found at even higher rates, approaching 80% of cases." (PMID 41169667, 2025). "It is well documented that downregulation of the MGMT gene is reported in a variety of tumor types, including gliomas, colorectal cancers, and lung cancers." (PMID 40895460, 2025). "The methylation status of the MGMT (O6-methylguanine-DNA methyltransferase) promoter is a crucial biomarker in gliomas, particularly in predicting the response to temozolomide (TMZ) chemotherapy." (PMID 40636690, 2025). "This likely reflects the incorporation of MGMT testing into standardized NCCN guidelines for high grade gliomas in 2013." (PMID 39907975, 2025). "In the case of gliomas, MGMT promoter methylation is more common in secondary than in primary tumors (73% vs. 43%)." (PMID 40428422, 2025). "MGMT promoter (MGMTp) methylation downregulates the protein synthesis of the MGMT protein and, by proxy, DNA repair, which enables alkylating agents to exert more damage to the malignant glioma cells." (PMID 40560010, 2025). "In this study we knocked-out (KO) the MGMT gene in U1242 GBM cells using CRSPR-Cas9 and also knocked-down (KD) MGMT mRNA expression in U1242 and additional glioma cell lines by siRNA." (PMID 40336841, 2025). "MGMT-methylated gliomas showed decreased DSC rCBV, whereas unmethylated brain gliomas demonstrated increased DCE Ktrans and ve." (PMID 40870498, 2025). "For example, MGMT overexpression induces resistance to gemcitabine in pancreatic cancer, to cisplatin in colorectal cancer and to temozolomide in glioma and estrogen receptor positive breast cancer." (PMID 40061896, 2025). "RD and DL offer transformative potential for non-invasive prediction of MGMT promoter methylation in gliomas." (PMID 39941181, 2025). "We subsequently surveyed 3 molecular signatures with positive prognostic significance across different age groups in glioma: IDH1/2-mutation, MGMT-methylation, and 1p19q codeletion." (PMID 39164213, 2025). "The PPVII-TMZ combination exhibited marked synergism in glioma models, particularly in overcoming O6-methylguanine-DNA methyltransferase (MGMT)-mediated chemoresistance." (PMID 40672368, 2025). "This regulation is exploited clinically to indirectly predict MGMT protein expression in patient glioma samples in order to gauge patient response to TMZ or other alkylating agents." (PMID 40336841, 2025).
glioma (continued). "Similar to a subtype of gliomas susceptible to TMZ treatment, the MGMT gene in TK6 cells is epigenetically inactivated." (PMID 39656916, 2025). "Nevertheless, several clinical investigations have observed positive outcomes when using platinum drugs in gliomas that express MGMT." (PMID 40336841, 2025). "The functional role of gene‐body methylation has been proven in the regulation of mRNAs, as very recently demonstrated for the MGMT mRNA that was found positively correlated with body methylation and negatively correlated with promoter methylation in gliomas." (PMID 40987757, 2025). "To evaluate the robustness and clinical relevance of MGMT-Net beyond internal validation frameworks, we assessed its performance on an external dataset of 200 glioma cases from three institutions: UCSF, NYU, and UTSW." (PMID 41007223, 2025). "This novel feature set was combined with established radiomics to build models for predicting O6-methylguanine-DNA methyltransferase (MGMT) methylation status, isocitrate dehydrogenase (IDH) mutation status, and Overall Survival (OS) time of glioma patients." (PMID 41561752, 2025). "On the other, EpiGnostix recognized ACP-B as a more heterogeneous cluster of samples, with inflammatory reactive tissue and low-grade glial tumors and MGMT status variability." (PMID 40575267, 2025). "Nonetheless, the potential of targeted RNA methylation therapy is substantial, particularly in light of the extensive clinical application of TMZ chemotherapy for gliomas characterized by high MGMT methylation, which theoretically enhances its feasibility." (PMID 40469294, 2025). "For instance, miR-370-3p has been shown to suppress MGMT expression in glioma by targeting its mRNA, contributing to TMZ resistance and malignant progression." (PMID 40895460, 2025). "While MGMT promoter-methylated gliomas are responsive to TMZ, a characteristic resistance mechanism of mismatch repair loss often emerges, resulting in recurrent drug-resistant disease." (PMID 41169667, 2025). "Functionally, spermine promoted the proliferation of TMZ-resistant glioma cells and was found to increase MGMT expression." (PMID 41244832, 2025). "Treatments for GBM, IDH-wild-type, and WHO grade 4 gliomas differ based on prognostic factors such as age, Karnofsky performance status (KPS), and MGMT gene mutation status." (PMID 40746950, 2025). "Glioma patients with MGMT promoter methylation are more sensitive to chemotherapy and have longer survival time." (PMID 40757022, 2025). "The DWI/ADC sequence contributes to genetically differentiating gliomas, since gliomas presenting a methylated MGMT promoter demonstrated higher ADC values." (PMID 40870498, 2025). "While biomarker-based therapies for gliomas are limited, O6-methylguanine-DNA methyltransferase (MGMT) is one well-established prognostic marker in GBM and is associated with improved response to the alkylating agent temozolomide (TMZ)." (PMID 41169667, 2025). "There were 36 patients with MGMT-unmethylated rHGGs: 6 with primary grade 3 gliomas and 15 with primary grade 4 gliomas who received the BAC regimen and 15 who received BEV alone." (PMID 40746950, 2025). "MGMT-methylated gliomas exhibited significantly higher ADCmin (0.86 vs. 0.74 × 10-3mm2/s, p = 0.013) and rADCmin (1.12 vs. 0.95, p<0.001)." (PMID 40958862, 2025). "The mutation status of isocitrate dehydrogenase (IDH) and the methylation status of the O6-methylguanine-DNA methyltransferase (MGMT) promoter are key biomarkers for glioma diagnosis and prognosis." (PMID 40757022, 2025). "Its increased expression correlates more strongly with OS than MGMT promoter methylation in G3 gliomas." (PMID 40428422, 2025). "In contrast, the prevalence of MGMT promoter methylation was similar across all adult patients, ranging between 43% and 49% across all gliomas (X2P = .091)." (PMID 39164213, 2025).
glioma (continued). "RBM39 depletion has been shown to suppress NF-κB signaling, and inhibition of NF-κB is known to reduce MGMT transcription and sensitize glioma cells to TMZ." (PMID 41300971, 2025). "This strategy triggered an immune-mediated anti-glioma response, particularly in patients with unmethylated MGMT promoters." (PMID 40806198, 2025). "Background/Objectives: The methylation status of the O6-methylguanine-DNA methyltransferase (MGMT) promoter in gliomas has emerged as a critical biomarker for prognosis and treatment response." (PMID 39941181, 2025). "We investigated the correlation between each cluster and various glioma subtypes associated with prognosis, including tumor grade, IDH status, 1p/19q codeletion status, transcriptome subtype, and MGMT promoter methylation status." (PMID 40090864, 2025). "The mechanism of this research argues that exosome‐mediated circWDR62 can promote TMZ resistance and virulent transformation of gliomas in vitro and in vivo by targeting the miR‐370‐3p/MGMT axis." (PMID 39950738, 2025). "While approximately 45% of adult high-grade gliomas exhibit MGMT promoter methylation, only about one-quarter of pediatric cases show this alteration." (PMID 41050069, 2025). "Multivariate independent prognostic analysis found that risk score, age, WHO classification, IDH status, 1p/19q codeletion, and MGMT promoter status were all indicators of survival in glioma patients." (PMID 41331166, 2025). "MGMT is highly expressed in a majority of human cancers including gliomas, and this elevated DNA repair interferes with the base mispairing and cytotoxic functions of anticancer alkylating agents." (PMID 39997039, 2025). "Better therapeutic response towards alkylating agents has been attributed to O6-methylguanine-DNA methyltransferase (MGMT) promoter hypermethylation in glioma patients, particularly those with GBM subtype." (PMID 40718795, 2025). "Exosome‐mediated conveyance of circWDR62 can improve TMZ obstruction and virulent tumour growth and metastasis by targeting the glioma miR‐370‐3p/MGMT axis in vitro and in vivo." (PMID 39950738, 2025). "As the only first-line chemotherapeutic drug, TMZ benefits a part of primary glioma patients with MGMT promotor methylation." (PMID 40914135, 2025). "The restriction of ADC-based MGMT prediction to IDH-wildtype gliomas necessitates preoperative molecular subtyping—a requirement increasingly addressable through non-invasive MRI biomarkers." (PMID 40958862, 2025). "This also suggests that the biological behavior of IDH wild-type gliomas is highly dependent on MGMT promoter methylation status." (PMID 40958862, 2025). "Administration of the BAC regimen for patients with primary grade 3 gliomas was beneficial for those with IDH-wild-type and MGMT-methylated gliomas in terms of OS and for those with MGMT-methylated gliomas in terms of both OS and PRS." (PMID 40746950, 2025). "This study tries to address these gaps by exploring the potential of combining conventional structural MRI, DCE, and DTI-derived radiomic features for predicting MGMT methylation status in gliomas." (PMID 39944537, 2025). "Specifically, among patients receiving BEV alone, those with MGMT-methylated gliomas showed the longest OS, 21 months." (PMID 40746950, 2025). "In this line, we found that ESURATAG-GS score is negatively correlated with MGMT gene methylation score in glioma patients from TCGA dataset." (PMID 40718795, 2025). "The MGMT promoter methylation status has been studied extensively for its impact on glioma prognosis and treatment response." (PMID 39834719, 2025). "KL-50 also warrants evaluation in pediatric high-grade gliomas, where MGMT silencing and TMZ responsiveness have historically been less well-defined, but the frequency of underlying germline MMR deficiency syndromes is increasingly recognized." (PMID 41169667, 2025).
glioma (continued). "As we know, the most prestigious example of DRG is MGMT in glioma, which was demonstrated as a prognostic indicator to predict the therapeutic advantage of chemotherapy regimen, for example, nitrosoureas and temozolomide." (PMID 40567901, 2025). "Methylation of the MGMT promoter is correlated with the sensitivity of glioma patients to alkyl chemotherapies." (PMID 40860684, 2025). "Although the methylation status of the O6-methylguanine-DNA methyltransferase (MGMT) promoter is considered a useful biomarker for predicting outcomes and guiding treatment decisions in glioma, its actual value in this regard is still a subject of debate." (PMID 40427005, 2025). "Other common epigenetic biomarkers in brain tumors such as glioma include O6-methylguanine-DNA methyltransferase (MGMT) promoter methylation, which is related to response to temozolomide (TMZ) therapy." (PMID 40959438, 2025). "MGMT (O6‐methylguanine‐DNA methyltransferase) promoter methylation is a molecular biomarker with prognostic, predictive, and clinical applications for glioma subtypes." (PMID 40792048, 2025). "In gliomas, high GLRX expression is associated with aggressive subtypes (wild-type IDH, methylated MGMT) and is involved in immune modulation." (PMID 41373732, 2025). "Brandes et al39 and Minniti et al40 reported that MGMT-methylated gliomas had increased distant relapses compared with unmethylated cases." (PMID 40705330, 2025). "For IDH-wildtype gliomas, where MGMT status critically determines temozolomide response, the clinically relevant predictive value of rADCmin (AUC = 0.78, sensitivity = 80.0%) offers tangible preoperative utility." (PMID 40958862, 2025). "This study introduced a radiomics-based ML model for noninvasive prediction of MGMT promoter methylation in high-grade gliomas, using multi-institutional multiparametric MRI." (PMID 41584616, 2025). "MGMT promoter methylation in IDH mutant gliomas is a result of metabolic alterations including increased production of 2-D-HG and genome-wide methylation." (PMID 40949165, 2025). "When considering PRS, patients with MGMT-methylated gliomas had a longer PRS of 12 months, while those with MGMT-unmethylated gliomas had a shorter PRS of only 8 months." (PMID 40746950, 2025). "The 9-ROI design prioritized sensitivity to focal diffusion restriction – a critical factor for MGMT prediction in IDH-wildtype gliomas where cellular heterogeneity is pronounced." (PMID 40958862, 2025). "Although ADC values can be used for glioma grading and IDH mutation prediction, their utility for identifying the methylation status of MGMT promoters remains controversial." (PMID 40958862, 2025). "For instance, in glioma, the activity of O6-methylguanine-DNA methyltransferase (MGMT) is positively correlated with resistance to temozolomide (TMZ), highlighting the potential role of methylation modifications in tumor drug resistance." (PMID 40018039, 2025). "MGMT promoter methylation status is determined in routine formalin-fixed, paraffin-embedded glioma tumor specimens, usually by bisulfide treatment of tumor DNA followed by DNA sequencing." (PMID 40336841, 2025). "Epigenetic regulation mediated by STING promoter methylation can modulate glioma immune responses, and this process is reversible by MGMT inhibitors." (PMID 40927709, 2025). "In 2008, it was first concluded that MGMT promoter methylation is a recognized test indicator for predicting the efficacy of TMZ in the treatment of glioma." (PMID 40469294, 2025). "All four selected patients were diagnosed with MGMT-methylated IDH wild-type grade 4 gliomas, following the WHO Classification of Tumors of the Central Nervous System criteria by the Pathology Department." (PMID 41009470, 2025). "Precision oncology in CNS cancers is made possible by the molecular pathways covered, including EGFR amplification, IDH1/2 mutations, and MGMT promoter methylation." (PMID 41311621, 2025).